ZNF580 (zinc finger protein 580)
Description:
Involved in the regulation of endothelial cell proliferation and migration. Mediates H(2)O(2)-induced leukocyte chemotaxis by elevating interleukin-8 production and may play a role in inflammation. May be involved in transcriptional regulation.
Tractability: PROTAC: UniProt records ubiquitination sites on it; its protein half-life has been measured.
Gene: Protein-coding gene on chromosome 19 (55,635,003 to 55,643,470, forward strand). Ensembl gene ENSG00000213015.
Subcellular location: Nucleus
Subcellular location (Human Protein Atlas): Nucleoplasm
Gene Ontology:
Molecular function: protein binding; sequence-specific double-stranded DNA binding; DNA-binding transcription activator activity, RNA polymerase II-specific; DNA-binding transcription factor activity, RNA polymerase II-specific; RNA polymerase II cis-regulatory region sequence-specific DNA binding
Biological process: cellular response to hydrogen peroxide; positive regulation of endothelial cell migration; positive regulation of endothelial cell proliferation; positive regulation of gene expression; positive regulation of interleukin-8 production; positive regulation of leukocyte chemotaxis; regulation of transcription by RNA polymerase II; positive regulation of transcription by RNA polymerase II
Cellular component: nucleus; chromatin
Genetic constraint (gnomAD): Loss-of-function variants: 1 observed, 0.71 expected, observed/expected ratio (o/e) 1.4, 90% interval 0.31 to 1.91. That is too few expected variants to judge how well the gene tolerates losing a copy. Missense variants: 268 observed, 163.78 expected, observed/expected ratio (o/e) 1.64, 90% interval 1.48 to 1.81. Synonymous variants: 135 observed, 78.39 expected, observed/expected ratio (o/e) 1.72, 90% interval 1.49 to 1.94.
Homologues: Orthologues: chimpanzee ZNF580 (100% identical), pig ZNF580 (99% identical), dog ZNF580 (98% identical), guinea pig ZNF580 (98% identical), mouse Zfp580 (97% identical), rat Zfp580 (97% identical). Paralogues in human: ZNF581 (52% identical), ZNF524 (39% identical), ZBTB49 (25% identical), FEZF1 (23% identical), PRDM13 (23% identical), ZBTB7B (23% identical), FEZF2 (22% identical), BCL6B (20% identical), BCL6 (20% identical), ZBTB21 (19% identical), ZNF683 (19% identical), GFI1 (18% identical), and 16 more.
Diseases named in the same sentence as ZNF580 in open-access papers:
ZNF580 is named in the same sentence as 7 diseases in open-access papers, as found by Europe PMC text mining. Sharing a sentence is not in itself a finding about the gene and the disease. The quoted sentences say what the papers report.
atherosclerosis (1 paper, 2021). A disease characterized by the build-up of fatty material and calcium deposition in the arterial wall resulting in partial or complete occlusion of the arterial lumen. "So, ZNF580 could regulate BP and have influences on some cardiovascular diseases, such as hypertension, atherosclerosis and so on." (PMID 34586716, 2021).
cardiac hypertrophy (1 paper, 2024). "Previous reports have established that zinc finger protein 580 (ZFP580) can inhibit cardiac hypertrophy in H9c2 cells by preventing hypoxia-induced apoptosis through the TGF-β1/Smad signaling pathway." (PMID 38970022, 2024).
melanoma (1 paper, 2023). A malignant, usually aggressive tumor composed of atypical, neoplastic melanocytes. "The heatmap was used to demonstrate the expression levels of the genes TBX21, ZNF799, HEY2, ZNF580, IRF4, CREB3, and ZNF93 during the pseudotime trajectories of four distinct subtypes of melanoma cells." (PMID 37435067, 2023).
Sepsis (1 paper, 2018). Sepsis is defined as life-threatening organ dysfunction caused by a dysregulated host response to infection. "This suggests cooperation between ZNF580 and NFκB, which could play a role during sepsis." (PMID 30386182, 2018).
Stroke (1 paper, 2022). Sudden impairment of blood flow to a part of the brain due to occlusion or rupture of an artery to the brain. "In this study, we evaluated the effects of zinc finger protein 580 (Zfp580) on endocrine and paracrine Igf1 and Igfbp3 after stroke." (PMID 35557964, 2022).
ZNF580 also shares sentences with these, for which no sentence is quoted: cardiovascular diseases (1 paper); Hypertension (1).